CFTR (CF transmembrane conductance regulator)
Diseases named in the same sentence as CFTR in open-access papers (continued):
Sharing a sentence is not in itself a finding about the gene and the disease.
cyst (continued). "Further cyst progression involves activation of multiple pathways, leading to increased epithelial tubular proliferation, CFTR-mediated fluid secretion of water and chloride, and abnormal matrix deposition with quintessential myofibroblast and macrophage infiltration." (PMID 39940890, 2025). "Interestingly, a recent report showed that the application of the CFTR-corrector VX-809 (Lumacaftor) in a Pkd1 knockout and the Pkd1RC/RC mouse model reduced cyst growth." (PMID 37686084, 2023). "Apical Cl− transport by CFTR drives net fluid secretion into the cyst lumen in response to cAMP." (PMID 35979967, 2022). "Furthermore, panduratin A reduced renal epithelial secretion of chloride and subsequently decreased cyst expansion via the inhibition of the CFTR transport function." (PMID 35457146, 2022). "Since CFTR plays a role in cyst enlargement, it is imperative to investigate whether panduratin A could inhibit CFTR-mediated chloride secretion leading to decreased renal cyst enlargement in PKD models." (PMID 35457146, 2022). "It inhibited cyst growth in cell culture by CFTR degradation in proteasome." (PMID 35328738, 2022). "Moreover, CFTR inhibitors reduced cyst progression and preserved renal function in Pkd1 knockout mice." (PMID 35457146, 2022). "Additionally, panduratin A slowed cyst expansion via inhibition of the protein expression and transport function of CFTR." (PMID 35457146, 2022). "Considering that panduratin A treatment reduced MDCK-derived cyst growth, we next sought to examine whether the inhibitory effect of panduratin A on cyst growth was a result of CFTR-mediated chloride secretion inhibition." (PMID 35457146, 2022). "We have been studying cyst inflation using the zebrafish Kupffer’s vesicle (KV) as model system because we previously demonstrated that knocking down polycystin 2 (PC2) induced a CFTR-mediated enlargement of the organ." (PMID 34445719, 2021). "Therefore, as the lack of calcium homeostasis raises the intracellular levels of cAMP in ADPKD cells, CFTR has been pointed to as a downstream effector of cAMP in cyst growth." (PMID 34445719, 2021). "CFTR and purinergic channels in the apical membrane of the renal tubules mediate the conduction of chloride and bicarbonate across the plasma membrane, and it has been postulated that CFTR plays a role in cyst growth where inhibitors of CFTR retard cyst enlargement in animal model." (PMID 31488014, 2019). "In human ADPKD cells, elevated intracellular cAMP activates cystic fibrosis transmembrane conductance regulator (CFTR)-mediated Cl− secretion and B-Raf/MEK/ERK signaling, causing fluid secretion and increased proliferation of cyst-lining epithelial cells, respectively." (PMID 29563577, 2018). "Abnormal proliferation of the cyst-lined epithelium and increased intra-cystic fluid secretion via the cystic fibrosis transmembrane conductance regulator (CFTR) may contribute to cyst growth in ADPKD." (PMID 30134806, 2018). "Favouring its use, KV volume can be easily determined by in vivo imaging offering a live readout for screening compounds and genes that may prevent cyst enlargement through CFTR inhibition." (PMID 26432887, 2015). "Triggering Cl− and water secretion towards the cyst lumen, CFTR promotes cyst inflation." (PMID 26432887, 2015). "Allowing the measurement of its volume as a live readout, it offers an excellent in vivo model for screening compounds and genes that may slow down cyst enlargement through CFTR inhibition." (PMID 26432887, 2015). "Therefore, we gave a step forward and tested the effect of a specific inhibitor of CFTR, thiazolidinone (CFTRinh-172), which was shown to slow down in vitro cyst enlargement." (PMID 26432887, 2015). "Indeed, renal cAMP levels are elevated in ADPKD mice models and in human cyst epithelial cells and have been suggested as one possible reason for the stimulation of CFTR." (PMID 26432887, 2015).
cyst (continued). "Moreover, PPARγ agonists appear to be effective not only in the kidney but in other tissues where cyst formation and growth are dependent on CFTR-driven ion and fluid secretion." (PMID 21052534, 2010). "Furthermore, steviol has been found to reduce MDCK cyst formation and growth by directly inhibiting CFTR chloride channel activity and reducing CFTR expression, particularly by promoting the proteasomal degradation of CFTR." (PMID 40136708, 2025). "The authors of this study did not mention the exact mechanism of pioglitazone for this reduction in the cyst size; however, they postulated that it could be because of the inhibitory effect on the expression of apical CFTR in the kidney because of pioglitazone agonistic effect on PPAR-γ." (PMID 33308138, 2020). "However, expression of CFTR protein in PKD cysts is highly heterogeneous and it is therefore postulated that additional ion channels other than CFTR might also attribute to electrolyte secretion that leads to cyst growth." (PMID 28197498, 2016). "This suggests that inhibitors of the CFTR Cl-channel might retard cyst growth." (PMID 28197498, 2016). "Therefore, it is believed that cyst formation and fluid accumulation in renal cysts are caused by the disruption of intracellular Ca+2 homeostasis through dysfunctional TRP channels and active chloride secretion through CFTR, which is stimulated by the cAMP/PKA pathway." (PMID 40136708, 2025). "Tolvaptan reduces cAMP levels, thereby limiting cyst fluid secretion, while metformin activates AMPK, inhibiting proliferative and secretory pathways such as mTOR and CFTR." (PMID 41254555, 2025). "Mechanistically, cAMP-activated protein kinase A (PKA) is known to activate CFTR, thus linking increased cAMP in ADPKD with cyst progression." (PMID 40722835, 2025). "It works by activating AMPK, which inhibits both the CFTR (cystic fibrosis transmembrane conductance regulator) and mTOR pathways through the phosphorylation of TSC2 (tuberin), potentially impacting cyst growth and renal function." (PMID 39200287, 2024). "Chloride transport by CFTR in renal cyst epithelium contributes to cyst fluid accumulation in ADPKD; inhibition of CFTR attenuates this process." (PMID 36615184, 2023). "As H2-GMZ blocked both cell proliferation and CFTR-mediated fluid secretion in ADPKD cells, we examined the effectiveness of H2-GMZ in inhibiting cAMP-dependent cyst growth and enlargement in mouse embryonic kidneys in organ culture." (PMID 35979967, 2022). "The proton pump inhibitor lansoprazole also reduced the cyst growth in vitro and in PCK rats by down-regulation of CFTR." (PMID 35328738, 2022). "One of the Hsp90 client proteins, the Cl− channel CFTR, plays an important role in the pathogenesis of ADPKD by mediating fluid secretion into the cyst lumen, and CFTR inhibitors have proven effective in reducing cyst growth." (PMID 35979967, 2022). "CFTR blockers (glibenclamide, NPPB, genistein) have been shown to reduce cyst growth and cAMP stimulated chloride currents in MDCK cyst in collagen gel." (PMID 36120538, 2022). "Based on our results we consider that this zebrafish organ system offers great potential for screening molecules that interfere with CFTR trafficking, stability and channel activity in preventing ADPKD cyst growth." (PMID 34445719, 2021). "The cystic fibrosis transmembrane conductance regulator (CFTR, OMIM 602421) is a key player in the cyst inflation process, being expressed and activated in ADPKD cyst-lining cells." (PMID 34445719, 2021). "Transepithelial chloride secretion through cystic fibrosis transmembrane conductance regulator (CFTR) and TMEM16A (anoctamin 1) are known to drive cyst enlargement." (PMID 32859916, 2020). "In summary, we found that pharmacological concentrations of steviol retarded cyst progression in an in vitro MDCK cell model, in part, by reducing CFTR expression levels via proteasome-mediated CFTR degradation." (PMID 23536832, 2013).
cyst (continued). "KCa3.1 activation or inhibition in cultured human ADPKD cyst epithelial cells modulates CFTR-mediated Cl– secretion without affecting cell proliferation." (PMID 41122971, 2025). "Research involving kidney epithelial cell cultures and PKD mouse models has shown that metformin inhibits mTOR signaling and the cystic fibrosis transmembrane conductance regulator (CFTR), reducing epithelial proliferation and secretion, thereby slowing cyst growth." (PMID 39339816, 2024). "Taken together, in mouse studies, ANO1 is a dominant driver of secretion-dependent cyst enlargement, while we also found that knockout of CFTR had no significant impact on cyst growth." (PMID 37686084, 2023). "Additionally, several lines of evidence illustrate that the cystic fibrosis transmembrane conductance regulator (CFTR) chloride channel is important for regulating fluid accumulation and electrolytes in ADPKD cyst lumens." (PMID 35457146, 2022). "In an orthologous mouse model of human ADPKD (Pkd1flox/flox;Pkhd1-Cre), stevioside and steviol inhibited the CFTR expression and mTOR/S6K proteins by activating AMP-activated protein kinase, thereby delaying the cyst development through inhibiting proliferation of renal epithelial cells." (PMID 33986666, 2021). "Additionally, it would also provide two complimentary platforms for measuring CFTR responses from the same population: ACC using the FLIPR assay and FSK-induced cyst swelling." (PMID 34764255, 2021). "For instance, CFTR inhibition could reduce cyst growth and kidney enlargement in patients with autosomal dominant polycystic kidney disease (ADPKD), suggesting that ABBV-2737 may be repurposed for other diseases where CFTR inhibition is advantageous." (PMID 39996840, 2025). "Therefore, it would be interesting to see if the cysts all express CFTR in the apical membrane domain and NKCC1 in the basolateral membrane with preserved polarity, as suggested by the hypothesis of cyst fluid secretion." (PMID 38339183, 2024). "However, the ADPKD-protective effect provided by CF was not confirmed in a subsequent report, and CFTR expression in isolated ADPKD cyst cells was shown to be very heterogeneous." (PMID 37686084, 2023). "In addition, pioglitazone, a peroxisome proliferator-activated receptor γ (PPARγ) agonist inhibited vasopressin-induced chloride secretion through reducing CFTR mRNA levels in MDCK-C7 cell line and suppressed cyst progression by decreasing apical CFTR expression in PCK rodent model of PKD." (PMID 23536832, 2013). "It is therefore not entirely clear whether inhibiting CFTR slows down cyst progression." (PMID 37686084, 2023). "Furthermore, the CFTR (cystic fibrosis transmembrane conductance regulator), the Ca2+-activated chloride channels TMEM16A (Anoctamin 1), but also the SLC member Slc12a2 have been identified as crucial aggravating co-factors for cyst enlargement in polycystic kidney disease." (PMID 35252349, 2022). "Three of these compounds, Bosutinib, Vermurafenib and the CFTR inhibitor IOWH-032, which equally reduced the viability of both wt and Pkd1-null cell types (as ΔAUC did not pass the cutoff), reduced cyst formation." (PMID 32144367, 2020).
diabetes (59 papers, 2012 to 2026). "The CFTR genotype holds the potential to predispose individuals to diabetes through various mechanisms." (PMID 38136081, 2023). "There is research suggesting that CFTR loss-of-function drives impaired insulin secretion; however, there is also evidence that the resultant diabetes occurs solely as a consequence of pancreatic inflammation." (PMID 35769082, 2022). "Given that not all individuals with CF develop CFRD raised the question as to the role of CFTR mutations in diabetes development." (PMID 35769082, 2022). "One study found that mice with a CFTR mutation were prone to developing diabetes after mild beta-cell injury." (PMID 35887806, 2022). "We took note of the lower amount of this FA in patients with Z-scores for body weight and height ≤−2, with two severe mutations of the CFTR gene, with liver disease and diabetes." (PMID 28106773, 2017). "Moreover, a strong correlation exists between the type of CFTR mutation and the development of diabetes." (PMID 34566890, 2021). "Furthermore, CFTR dysfunction makes beta-cells more susceptible to oxidative stress with subsequent apoptosis of this cell line and development of diabetes." (PMID 33810109, 2021). "CFTR genotype may predispose one to diabetes through exocrine pancreatic dysfunction or through a more direct role on islets." (PMID 33810109, 2021). "Understanding the CFTR mutation type and the usage of pancreatic enzyme is important to adjust for equal sampling distribution because both factors can potentially affect vitamin D deficiency and diabetes onset." (PMID 34836301, 2021). "In addition, patients carrying severe mutations such as class I and II mutations have a higher risk of diabetes and pancreatic insufficiency compared to those with milder CFTR mutations." (PMID 34394004, 2021). "As severe CFTR genotype increases the risk of diabetes independently of pancreatic exocrine dysfunction, a screening for prediabetes is mandatory in patients with two severe CFTR mutations, particularly F508del, and insulin supplementation seems a rational therapy to consider." (PMID 33810109, 2021). "Genetics studies on twins and siblings with CF have demonstrated that the risk of diabetes correlates with the degree of gene-sharing among related CF patients, indicating that genetic factors different from the CFTR genotype contribute to the development of CFRD." (PMID 33810109, 2021). "In addition, this system can be used to study CF-related diabetes and glucose imbalance, measure the variability of blood glucose, determine the correlation between glucose levels and CFTR mutation type, and screen small-molecule drugs that improve glucose abnormalities in individuals with CF." (PMID 35764957, 2022). "The advent of CFTR modulators and the emergence of novel diabetes technologies have created new opportunities to optimize glycemic control and enhance quality of life for PwCFRD." (PMID 41552835, 2026). "The development of cystic fibrosis-related diabetes is contingent upon the residual function of CFTR." (PMID 38611676, 2024). "Dysfunctional CFTR channels render beta cells more vulnerable to oxidative stress, a condition that can subsequently lead to apoptosis and the initiation of diabetes." (PMID 38136081, 2023). "There are thus far few specific data on the impact of CFTR modulators on either the incidence or severity of diabetes." (PMID 34926166, 2021). "The onset of diabetes in CF is highly influenced by the specific CFTR genotype; in fact, a higher prevalence of diabetes was described in patients with more severe CFTR genotypes, unlike mutations causing mild CFTR dysfunction." (PMID 33810109, 2021). "Glyburide targets CFTR gene and it is second-generation sulfonylureas which approved for diabetes management." (PMID 33841528, 2020). "Beyond its ability to potentiate CFTR channel gating, genistein reportedly has a broad activity on a variety of diseases including cancer, insulin resistance, diabetes, obesity, chronic inflammation." (PMID 30981209, 2019).
diabetes (continued). "We assessed Fas’ profile (gas chromatography/mass spectrometry), CF transmembrane conductance regulator (CFTR) genotype, spirometry, fecal elastase-1, body height and weight Z-scores, liver disease, diabetes and colonization by Pseudomonas aeruginosa." (PMID 28106773, 2017). "CF pancreatic disease and its associated diabetes have been particularly difficult to study in mice lacking the CFTR gene." (PMID 39687022, 2024). "Although this chip cannot fully mimic the physiological and pathological of in vivo pancreatic system, this finding reveals that the critical role of CFTR in maintaining endocrine function, which will offer important insight into the etiology of CF-related diabetes." (PMID 35764957, 2022). "It was reported that a percentage of patients having the same CFTR genotype develop diabetes, and that, even among CFRD individuals with identical severe CFTR genotypes, there may be wide variation in the onset of diabetes." (PMID 33810109, 2021). "Dietary Asn supplementation may particularly benefit CFTR-null homozygotes or compound heterozygotes, who frequently present with diabetes at later stages of their disease." (PMID 26178806, 2015). "In the absence of a functional CFTR channel, pancreatic acinar cell loss, severe inflammation, fibrosis, and adipogenesis alter the microenvironment of the pancreatic islets and ductal epithelium leading to pancreatic insufficiency and diabetes." (PMID 39687022, 2024). "The temporal outcomes of CFTR modulator use in the context of longer-term pancreatic complications including CF-related diabetes and malignancy are yet to be established, but with demonstrable benefits in the short-term setting, positive effects may be anticipated." (PMID 35832587, 2022). "In addition to pancreatic fibrotic damage, determined largely by CFTR dysfunction, other factors may contribute to development of diabetes in CF." (PMID 33810109, 2021). "On the basis of these results, it was hypothesized that early use of a CFTR corrector in very young children, who still have the presence of considerable beta-cell mass, or even before birth, could delay or prevent the development of diabetes." (PMID 33810109, 2021). "Here we report that short-term CFTR inhibition does not cause clinically significant glucose abnormalities, nor is it associated with spontaneous development of diabetes, a long-term defect in the secretory capacity of islets, pancreatic inflammation or fibrosis." (PMID 31375720, 2019). "The presently demonstrated role of CFTR in regulation of glucagon-production related genes (i.e., glucagon and PC2) may underlie the pathogenesis of the glucagon level disruption seen in CF patients with diabetes." (PMID 29204121, 2017). "F508del/L138ins compound heterozygotes do not have meconium ileus, CF-associated diabetes mellitus, severe liver damage and chronic Pseudomonas aeruginosa (Pseudomonas aeruginosa) infection is much less common than those who are homozygous for the most common pathogenic CFTR gene variant, F508del." (PMID 37510311, 2023). "In light of the present findings, we propose that abnormal CFTR, either by its mutation as seen in CF or by its abnormal upregulation as seen in PCOS, may be one of the underlying causes for disordered glucose metabolism, leading to diabetes or insulin resistance seen in both diseases." (PMID 29204121, 2017). "CFTR is not expressed by the endocrine pancreas but fibrosis and CFTR dysfunction in the ducts trigger the emergence of diabetes as the major co-morbidity in CF." (PMID 37025483, 2023). "This case of hypoglycaemia associated with CFTR modulator therapy in a patient without preexisting diabetes suggests that CFTR modulator therapy has the potential to directly affect glucose homeostasis." (PMID 38161769, 2023). "Pancreatic insufficiency correlates with the CFTR genotype, even if not all patients with pancreatic exocrine disease develop diabetes." (PMID 33810109, 2021).